KRT8P5 (keratin 8 pseudogene 5)
Gene: Processed pseudogene on chromosome 18 (44,320,800 to 44,322,257, reverse strand). Ensembl gene ENSG00000267573.
Diseases named in the same sentence as KRT8P5 in open-access papers:
KRT8P5 is named in the same sentence as 1 disease in open-access papers, as found by Europe PMC text mining. Sharing a sentence is not in itself a finding about the gene and the disease. The quoted sentences say what the papers report.
Hypertension (1 paper, 2017). The presence of chronic increased pressure in the systemic arterial system. "Three detected genes were recognized by previous studies, and the other 5 loci/genes (MAN1A1, LMO3, NPAP1/SNRPN, DNAL4, and RNA5SP455/KRT8P5) were novel findings, which had no strong main effect on hypertension and could not be easily identified by single-locus genome-wide studies." (PMID 28642868, 2017).